IL4I1 (interleukin 4 induced 1)
Diseases named in the same sentence as IL4I1 in open-access papers (continued):
Sharing a sentence is not in itself a finding about the gene and the disease.
glioma (continued). "Moreover, univariate Cox regression analysis of the CGGA dataset showed that IL4I1 level was an independent factor (low vs. high, p < 0.001) for predicting glioma patients’ prognosis." (PMID 38250074, 2023). "Therefore, we established a co-culture model to interrogate the effects of IL4I1 in M2-like macrophages on the proliferation, migration, and invasion of glioma cells in vitro." (PMID 38250074, 2023). "IL4I1 (part of our risk model) is able to activate AHR through the production of indole metabolites and canine, and is associated with decreased survival rate, promotion of cancer cell movement, and inhibition of adaptive immunity in people with glioma." (PMID 36407768, 2022). "This is consistent with our study, which showed that IL4I1 plays a tumor-promoting role in gliomas." (PMID 36407768, 2022). "Then, four genes (IL4I1, CYP1A1, OGDHL, and ASMT) were screened out by univariate and multivariate cox regression analysis of tryptophan metabolism genes, and a risk score model for predicting the overall survival (OS) of glioma patients was constructed." (PMID 36407768, 2022). "However, the mechanism that removes methylation from the IL4I1 promoter in TAMs in glioma is unknown." (PMID 39516356, 2024). "A negative association was noticed between the glioma grade and DNA promoter methylation of IL4I1." (PMID 38250074, 2023). "Notably, IL4I1 expression was significantly lower in glioma cells (U87, LN229, and U251)." (PMID 38250074, 2023). "Furthermore, analyses of IL4I1 promoter methylation indicated that methylated CpGs of IL4I1 indeed decreased with tumor grade, and hypomethylation was involved in a poorer prognosis in glioma patients." (PMID 38250074, 2023). "We performed PCR in clinical samples including six normal brain tissues, 22 low grade gliomas (LGG), and 51 GBMs and found that the expression level of IL4I1 in GBM was significantly higher compared with that in normal brain tissues and LGG." (PMID 40071723, 2025). "Recent studies have demonstrated that IL4I1 activates AhR more potently than IDO1 and TDO2, generating indole metabolites and quinolinic acid that promote tumor progression in gliomas and leukemia by enhancing cancer cell motility and suppression immunity." (PMID 40559961, 2025). "The correlation between IL4I1 protein or mRNA and prognosis was also observed in KIRC, glioma, COAD, and BRCA." (PMID 38691253, 2024). "Lastly, we determined that IL4I1, IDO1, and AHR are significantly higher in GBMs compared to low-grade gliomas." (PMID 38937431, 2024). "Moreover, IL4I1 could also promote glioma cell migration and metastasis." (PMID 38057821, 2023). "We analyzed the TCGA database to examine IL4I1, IDO1, and AHR expression and their contribution to glioblastoma and low-grade glioma (LGG) patients’ clinical outcome." (PMID 37986881, 2023). "The construction of our predictive model was based on the expression levels of four genes (IL4I1, CYP1A1, OGDHL, and ASMT) in glioma tissues." (PMID 36407768, 2022). "However, IL4I1 could thus represent a new target for the treatment of glioma." (PMID 36407768, 2022). "At the same time, we verified the expression of IL4I1, CYP1A1, OGDHL, and ASMT four genes in glioma specimens and cell lines in GES4260 and GES15824." (PMID 36407768, 2022). "Combined with the results of our univariate Cox analysis, we can conclude that IL4I1 plays a tumor-promoting role and CYP1A1, OGDHL, and ASMT all play protective roles in gliomas." (PMID 36407768, 2022). "There is a negative correlation between temozolomide and IL4I1 expression, and temozolomide is commonly utilized as a chemotherapeutic drug in patients with gliomas." (PMID 38691253, 2024). "In the present study, we demonstrated that IL4I1 was mainly expressed on M2-like macrophages but not on glioma cells." (PMID 38250074, 2023).
glioma (continued). "We found that IL4I1 was highly expressed in glioma cell lines (LN018, LN215, LN229, and LN319), CYP1A1 was low expressed in glioma cell lines (LN215, LN229, LN319, and BS149), OGDHL was low expressed in LN018, and ASMT was lowly expressed in glioma cell lines (LN018, LN215, LN229, LN319, and BS149)." (PMID 36407768, 2022). "The expression levels of IL4I1 are correlated with reduced survival in glioma patients, and high IL4I1-expressing tumors are characterized by an enrichment of suppressive immune cells (MDSCs) and Tregs; however, the major cell types expressing IL4I1 in glioma were not identified in this study." (PMID 39516356, 2024).
melanoma (17 papers, 2018 to 2025). A malignant, usually aggressive tumor composed of atypical, neoplastic melanocytes. "Additionally, the expression of IL4I1 in melanoma patients is positively associated with overall survival." (PMID 40583248, 2025). "Indeed, IL4i1 is associated with reduced immune responses toward malignancies and poor survival in several cancer types including melanoma, glioma, and ovarian cancer." (PMID 37196768, 2023). "Our findings indicate a positive correlation between tumor‐intrinsic IL4I1 expression and the expression of HLA‐A/‐B/‐C, B2M, and genes associated with CTL activation (GZMB, GZMA, CD8A, IFNG) in melanoma patients." (PMID 40583248, 2025). "In melanoma and ovarian cancer patients, IL4I1 expression or activity is additionally found to increase with disease progression or metastasis." (PMID 39211039, 2024). "In melanoma-challenged, tumor antigen-immunized mice, IL4I1 expression by tumor cells facilitates tumor outgrowth, which is mediated by suppression of the tumor antigen-specific CD8+ T-cell response." (PMID 39211039, 2024). "A retrospective analysis of IL4I1 expression in melanoma patients will determine its predictive value in response to immunotherapy (NCT04253080)." (PMID 34944851, 2021). "In a recent review, we addressed emerging questions about the impact of IL4I1 on B-cell functions in melanoma." (PMID 31330829, 2019). "In a model of spontaneous melanoma, IL4I1 expression and activity increases with disease progression, while IL4I1 deficiency enhances tumor control and associates with reduced G-MDSC and macrophage infiltration as well as enhanced CD4+ T-cell, CD8+ T-cell and B-cell infiltration into the tumor." (PMID 39211039, 2024). "Previous studies have shown that IL4I1 is highly expressed invarious human cancers, including ovarian, colorectal, melanoma, head-neckcancers, and B-cell lymphoma, where it may facilitate immune escape and isassociated with a poor prognosis." (PMID 39355609, 2024). "In contrast, knock-out of IL4I1 in B cells reduces the growth of melanoma cells in transplanted mice, which is accompanied by increased proportions of effector memory T cells and reduced proportions of regulatory T cells and G-MDSCs in the tumor microenvironment." (PMID 39211039, 2024). "IL4I1, expressed by CD11b+ myeloid cells, modifies the immune landscape in melanoma." (PMID 37844995, 2023). "Some studies have indicated that IL4I1 could promote the malignant progression of melanoma, KIRC, and LIHC by reprogramming the TME." (PMID 38250074, 2023). "The high transcriptional IL4I1 expression by MHCII+ CD163− TAMs in MeLiM pigs with regressing melanoma was unexpected, but may result from the enriched IFNγ, TNFα, IL12 and IL6 tumor microenvironment between R0 and R1 stages." (PMID 37526660, 2023). "Similarly, IL4I1 mRNA expression is higher in patients with metastatic melanoma compared to those with primary melanoma." (PMID 36765849, 2023). "Altogether, these data support a key role for IL4I1 in melanoma aggressiveness." (PMID 37526660, 2023). "Recent clinical data highlight IL4I1 as a new potential prognostic marker in human melanoma." (PMID 31330829, 2019). "Finally, we showed a clinical correlation between IL4I1 expression in primary cutaneous tumors and parameters of poor outcome in patients with melanoma." (PMID 31330829, 2019). "It was also associated with invasion of the sentinel lymph node, a higher melanoma stage, and rapid relapse and tended to correlate with shorter overall survival, specifically when considering cases in which the IL4I1+ cells were in close contact with tumor cells." (PMID 31330829, 2019). "Based on the FAM molecular subtypes, we identified the 6 FAMGs (ACSL5, ALOX5AP, CD1D, CD74, IL4I1, TBXAS1) that play vital regulatory roles in the melanoma TME." (PMID 36466837, 2022).
melanoma (continued). "Some researchers have found that IL4I1, as a prognostic biomarker, augments tumor growth by reprogramming TME in melanoma, kidney renal clear cell carcinoma (KIRC), and liver hepatocellular carcinoma (LIHC), which is attributed to its association with the movement and recruitment of leukocytes." (PMID 38250074, 2023). "When studying IL4I1 levels in ICB-treated advanced melanoma patients, it was noted that nivolumab therapy correlated with the induction of both IL4I1 and IDO1 and resulted in AhR activation." (PMID 34944851, 2021). "In the clinical significance of IL4I1, the authors found that IL4I1 expression and AHR activity were enhanced in primary cancer tissues and were higher in metastatic melanoma compared to primary melanoma." (PMID 33692337, 2021). "Indeed, we previously reported that IL4I1 limits the expansion of anti-tumor cytotoxic CD8 T cells and accelerates the escape of mouse melanoma from immune control." (PMID 33343572, 2020). "Similarly, tumoral IL4I1 overexpression reduces CD8+ T cell infiltration into tumors of non-immunized melanoma-transplanted mice, although it does not affect tumor growth likely due to the poorly immunogenic, highly aggressive nature of this model." (PMID 39211039, 2024). "In a second mouse model of spontaneous melanoma development, the genetic absence of IL4I1 delayed the appearance of primary tumors and metastases and favored tumor infiltration by T and B cells, while diminishing the infiltration by polymorphonuclear myeloid-derived suppressor cells." (PMID 31330829, 2019).
glioblastoma (12 papers, 2021 to 2025). The most malignant astrocytic tumor (WHO grade IV). "Interleukin 4‐induced 1 (IL4I1) is a novel anti‐ferroptosis regulator‐IL4I1 by regulating Nrf2 and serving as a ROS scavenger in glioblastoma multiforme (GBM)." (PMID 40071723, 2025). "Next, they treated glioblastoma (GBM) cells with IL4I1-derived metabolites, which increased the nuclear localization of AHR and enhanced AHR target genes transcription." (PMID 33692337, 2021). "Furthermore, we observed that IL4I1 was increased substantially in a glioblastoma (WHO IV) compared with an oligodendroglioma (WHO II) and anaplastic astrocytoma subtypes (WHO III)." (PMID 38250074, 2023). "We examined IL4I1, IDO1, and AHR expression in the TCGA database and their contribution to glioblastoma and low-grade glioma (LGG) clinical outcome." (PMID 38937431, 2024). "further suggests that IL4i1 activates the expression of AHR, IDO, and TDO2, which collectively suppress tumor immunity in the hypoxic TME of glioblastoma derived GBM cells, thereby promoting cancer progression." (PMID 38605962, 2024).
B-cell lymphomas (6 papers, 2019 to 2024). "were the first to propose that the novel immunosuppressive enzyme IL4I1, which is produced by the neoplastic cells of several B-cell lymphomas and by tumor-associated macrophages, is a prognostic biomarker and therapeutic target in cancer." (PMID 36466837, 2022). "Contrarily, although IL4I1 expression by macrophages is a common feature of B-cell lymphomas as well, several subtypes also frequently express IL4I1 in neoplastic cells, in keeping with its natural expression in B cells." (PMID 39211039, 2024). "The mRNA of IL4I1 was initially found to be overexpressed in a rare subtype of aggressive human B-cell lymphoma, primary mediastinal B-cell lymphoma (PMBL)." (PMID 31330829, 2019). "This suggests a dichotomous role for IL4I1 in solid tumors compared to B-cell lymphomas, which may be related to the physiological regulatory role of IL4I1 in B-cell activation, but requires further substantiating evidence." (PMID 39211039, 2024). "Then, a study on IL4I1 expression by immunochemistry in more than 30 types of human tumor tissues reported that IL4I1 expressed in almost all tumor-infiltrating macrophages, but only in specific types of cancers, such as mesothelioma and B cell lymphomas." (PMID 37434155, 2023). "Moreover, IL4I1 expression was observable in tumor cells in specific types of cancer, mainly mesothelioma and B cell lymphomas derived from germinal-center B cells, such as PMBL and follicular lymphoma." (PMID 31330829, 2019).
breast carcinoma (6 papers, 2020 to 2024). "Further studies are necessary to find out if the tryptophane–IL4I1–I3P pathway also exists in mammary carcinomas of pet rabbits." (PMID 39061522, 2024). "As an immune-associated enzyme, interleukin-4-induced-1 (IL4I1) was found overexpressed in tumor cells and to be a parameter predictive of poor prognostic in breast cancer and renal cancer." (PMID 37434155, 2023). "This suggests that activation of the tryptophane–IL4I1–I3P pathway could possibly contribute to breast cancer tumorigenesis as well." (PMID 39061522, 2024). "Significantly, IL4I1 TAMs abundance correlates with anti-PD1 treatment response in breast cancer." (PMID 36711732, 2023). "Furthermore, it has been shown that breast cancer may express not only IDO1, but also IL4I1." (PMID 39061522, 2024).
lung adenocarcinoma (5 papers, 2018 to 2025). A carcinoma that arises from the lung and is characterized by the presence of malignant glandular epithelial cells. "Thymol and anti-PD-1 antibodies therapy suppresses IL4I1 and AhR signaling in lung adenocarcinoma models." (PMID 40559961, 2025). "IL4I1 is a promising drug target for the combination immunotherapy in lung adenocarcinoma (LUAD)." (PMID 37655051, 2023).
malignant glioma (5 papers, 2018 to 2024). A grade III or grade IV glioma arising from the central nervous system. "IL4I1 exhibited specific overexpression on TAMs and tissues and promoted the progression of malignant gliomas." (PMID 38250074, 2023). "Interestingly, IL4I1 is secreted and found in serum where it promotes a tumor-prone microenvironment, increasing the concentration of metabolites in the patient’s biological fluids, including malignant gliomas patients’ cerebrospinal fluid." (PMID 38937431, 2024).
cutaneous melanoma (4 papers, 2023 to 2024). A primary melanoma arising from atypical melanocytes in the skin. "Our recent data also showed that IL4I1 expression is related to a microenvironment enriched in regulatory T cells and poor in granzyme B-positive CD8+ T cells in human primary cutaneous melanoma and is associated with a higher risk of poor outcome in patients." (PMID 37526660, 2023). "As a result, the high expression of IL4I1 in tumor cells promoted the immune escape in human primary cutaneous melanoma." (PMID 37434155, 2023). "Additionally, in human skin melanoma, IL4I1 influences patient survival and prognosis by modulating the local T cell response." (PMID 38691253, 2024). "Moreover, IL4I1 was found to play a critical role in the development of ovarian cancer, head-neck cancer, cutaneous melanoma, and ccRCC." (PMID 36866272, 2023).
Granuloma (4 papers, 2013 to 2020). A compact, organized collection of mature mononuclear phagocytes, which may be but is not necessarily accompanied by accessory features such as necrosis. "The IL4I1 gene encodes an immunosuppressive enzyme (L-phenylalanine oxidase) that inhibits T-cell proliferation via H2O2 production and is highly expressed in macrophages and DCs of granulomas from sarcoidosis and TB." (PMID 32373118, 2020). "This is consistent with the high levels of IL4I1 detected in the macrophage-derived cells and dendritic cells of tuberculosis granulomas, where it may reduce dissemination of the pathogen while limiting excessive Th1-cell activation." (PMID 31330829, 2019). "Accordingly, IL4I1 is strongly produced by dendritic cell and macrophage populations from chronic Th1 granulomas of sarcoidosis and tuberculosis, but not Th2 granulomas (schistosomiasis)." (PMID 31330829, 2019). "Because Th1 and Th2 cytokines control macrophage polarization and as IL4I1 is highly expressed in Th1 but not in Th2 granulomas, we tested the role of IL4I1 in macrophage plasticity and polarization." (PMID 26599209, 2015).
leukemia (4 papers, 2018 to 2025). A malignant (clonal) hematologic disorder, involving hematopoietic stem cells and characterized by the presence of primitive or atypical myeloid or lymphoid cells in the bone marrow and the blood. "However, a recent study reported serum IL4i1 amounts of up to 300 pg/ml in a mouse leukemia model." (PMID 33646117, 2021). "CLL is associated with an increased IDO1 expression and activity, but its pharmaceutical inhibition is not sufficient to control leukemia development in a mouse model of CLL, suggesting compensatory mechanisms, such as that of IL4I1, in place that maintain immunosuppression." (PMID 33920868, 2021).